MINK1 (misshapen like kinase 1)
Diseases named in the same sentence as MINK1 in open-access papers (continued):
Sharing a sentence is not in itself a finding about the gene and the disease.
osteoarthritis (1 paper, 2024). A noninflammatory degenerative joint disease occurring chiefly in older persons, characterized by degeneration of the articular cartilage, hypertrophy of bone at the margins and changes in the synovial membrane. "Another condition with pathogenesis that could be dependent on MINK1 is osteoarthritis, the most common disease of the joints." (PMID 39727954, 2024).
systemic lupus erythematosus (1 paper, 2024). An autoimmune multi-organ disease typically associated with vasculopathy and autoantibody production. "MINK1 has been also detected to be connected to systemic lupus erythematosus (SLE) risk." (PMID 39727954, 2024).
tumor (12 papers, 2017 to 2025). "Among the selected mRNAs, MINK1 mRNA was detected as altered in tumor tissues in comparison to the normal tissue samples." (PMID 39727954, 2024). "Overall, MINK1 probably plays a complex role in cancer, acting as a tumor suppressor, or contrarily, as a factor promoting aggressive phenotype of cancer cells depending on the case." (PMID 39727954, 2024). "Studies have found that the Hippo pathway kinase LATS1/2 in tumor cells can affect tumor growth, and MINK1 is involved in the expression of Hippo pathway kinase." (PMID 36303542, 2022). "The tumor growth, as measured by fluorescence intensity of primary tumors, was found to be significantly reduced in the MINK1 KO group with the treatment of 5FU." (PMID 36182968, 2022). "MINK1 induction could be considered a therapeutic strategy for ovarian cancer for induction of growth arrest in tumor cells." (PMID 39727954, 2024). "Tracking the expression of MINK1 may be useful in the identification of potential drug resistance in tumor cells." (PMID 39727954, 2024). "Further studies are needed to understand how environmental factors, such as the tumor microenvironment and the infiltration of the immune cells, may influence MINK1’s role in various cancers." (PMID 39727954, 2024). "This further confirms the potential importance of MINK1 expression assessment in tumor cells." (PMID 39727954, 2024). "The dual roles of MINK1 as both a tumor suppressor and a promoter of aggressive cancer phenotypes suggest that the function of MINK1 may depend on various factors and may be different in various cancers." (PMID 39727954, 2024). "Key genes identified in this subtype included SLBP, MBD1, MINK1, DPH1, and CSNK1D, which are noted in existing literature for their roles in tumor malignancy and progression, thereby reinforcing the reliability of the ac4C score." (PMID 39648231, 2024). "Combined deletion of MINK1 and MST1/2 could inhibit the activation of LATS1/2, improve tumor immunogenicity, and inhibit tumor growth." (PMID 36303542, 2022). "We also evaluated the MINK1 expression in drug-naive and post-CT non-responder paired tumor samples from the same patient and observed that the post–CT-treated tumor samples showed higher MINK1 expression." (PMID 36182968, 2022). "With the evaluation of clinical samples, the expression of MINK1 was found to be elevated in tumor tissues of chemotherapy non-responders as compared to chemotherapy responders." (PMID 36182968, 2022). "MINK1 and PLEKHM3 were significantly downregulated in GBM compared to non-tumor (p-values < 0.001)." (PMID 35877430, 2022). "Analysis of clinical samples demonstrated significantly higher MINK1 expression in the tumor tissues of chemotherapy non-responders as compared to chemotherapy responders." (PMID 36182968, 2022). "Moreover, MINK1 knockdown resulted in lowered tumor mass in response to 5FU treatment in mice, but no such effect was observed in the MINK1 WT group." (PMID 39727954, 2024). "The hazard ratios of LCLAT1 and CCDC43 are positive, indicating the anti- survival function of these genes, while the coefficients of other 5 genes are negative, including ENSG00000269386 (RAB11B-AS1), TOM1L2, AMPD3, MINK1 and WDTC1, indicating that they may be tumor suppressor genes." (PMID 28331188, 2017).
cancer (9 papers, 2020 to 2025). A tumor composed of atypical neoplastic, often pleomorphic cells that invade other tissues. "While mammalian MINK1 has been extensively characterized for its roles in cancer progression, cell fate determination, and innate immunity, the functional significance of MINK1 in teleost remains largely unexplored." (PMID 41200183, 2025). "Increased expression of STRN was found in different cancers, which induced cell cycle progression and invasiveness by activating downstream transcription factors, including misshapen-like kinase 1, RhoA, TRAF2, NCK-interacting protein kinase and PDGFRA." (PMID 38215077, 2024). "First, it has been suggested that the MINK1 kinase is involved, as it induces PRICKLE membrane localization, and MINK1 expression is elevated in chemoresistant carcinomas, thus suggesting its possible role in tumorigeneses." (PMID 37358815, 2024). "Recently, it is reported that MINK1 can regulate the planner cell polarity, which is essential for spreading of cancer cells." (PMID 36182968, 2022). "Eventually, the target gene MINK1 is upregulated, potentially leading to the migration of cancer cells to mid-stage CRC." (PMID 32211020, 2020). "Subsequently, the target gene MINK1 is upregulated, potentially leading to the migration of cancer cells to mid-stage CRC." (PMID 32211020, 2020). "Furthermore, upon phosphorylation by MINK1 (misshapen-like kinase 1), sNAIL1 binds to Rictor and mTORC2, forming a complex that activates mTORC2 to regulate cell adhesion and cancer cell migration." (PMID 40002810, 2025). "Also, cancer cells showed reduced distal migration from the primary site in the case of MINK1 KO 5FU treated group." (PMID 36182968, 2022). "The roles of CSNK1E and MINK1 in a variety of cancers have not yet been investigated." (PMID 33818013, 2021).
cardiovascular disease (2 papers, 2024).
neurodegenerative disease (2 papers, 2019 to 2024). A disorder of the central nervous system characterized by gradual and progressive loss of neural tissue and neurologic function. "In addition, modulating MINK1 activity in autoimmunity, neurodegenerative diseases, or malignancies could improve the clinical outcomes of patients." (PMID 39727954, 2024).
MINK1 also shares sentences with these, for which no sentence is quoted: amyotrophic lateral sclerosis (2 papers); infection (2); prostate tumours (2); schizophrenia (2); Arthritis (1); autism (1); bile duct cancer (1); cardiac diseases (1); Crohn disease (1); endometrial cancer (1); gout (1); HCMV infection (1); Hodgkin disease (1); immune diseases (1); injury (1); Insulin resistance (1); kidney clear cell carcinoma (1); osteoporosis (1); pancreatic cancer (1); pancreatic ductal adenocarcinoma (1); Parkinson disease (1); partial epilepsy (1); peritonitis (1); type II diabetes (1).